BEST3 (bestrophin 3)
Description:
Ligand-gated anion channel that allows the movement of chloride monoatomic anions across cell membranes when activated by calcium (Ca2+).
Synonyms: VMD2L3; MGC40411; MGC13168
Tractability: Antibody: UniProt places it where antibodies can reach, with medium confidence; UniProt predicts a signal peptide or a membrane-spanning region; its Gene Ontology location is reachable by antibodies, with medium confidence.
Gene: Protein-coding gene on chromosome 12 (69,643,360 to 69,699,476, reverse strand). Ensembl gene ENSG00000127325.
Subcellular location: Cell membrane
Pathways (Reactome):
Transport of small molecules: Stimuli-sensing channels
Gene Ontology:
Molecular function: intracellularly calcium-gated chloride channel activity; chloride channel activity; ligand-gated monoatomic anion channel activity; channel activity
Biological process: chloride transmembrane transport
Cellular component: plasma membrane
Genetic constraint (gnomAD): Loss-of-function variants: 36 observed, 37.29 expected, observed/expected ratio (o/e) 0.97, 90% interval 0.74 to 1.27. The upper end of that interval is the gene's LOEUF score, 1.27, which puts it in group 5 of 6, group 1 being the genes least tolerant of losing a copy. Missense variants: 718 observed, 800.82 expected, observed/expected ratio (o/e) 0.9, 90% interval 0.84 to 0.95. Synonymous variants: 265 observed, 296.5 expected, observed/expected ratio (o/e) 0.89, 90% interval 0.81 to 0.99.
Homologues: Orthologues: chimpanzee BEST3 (99% identical), macaque BEST3 (97% identical), mouse Best3 (85% identical), rat Best3 (85% identical), pig BEST3 (84% identical), rabbit BEST3 (84% identical), guinea pig BEST3 (83% identical), tropical clawed frog best3 (59% identical), dog BEST3 (54% identical), Drosophila melanogaster Best1 (32% identical), Drosophila melanogaster Best4 (28% identical), Drosophila melanogaster Best3 (27% identical), and 17 more. Paralogues in human: BEST1 (40% identical), BEST2 (40% identical), BEST4 (36% identical).
Diseases named in the same sentence as BEST3 in open-access papers:
BEST3 is named in the same sentence as 8 diseases in open-access papers, as found by Europe PMC text mining. Sharing a sentence is not in itself a finding about the gene and the disease. The quoted sentences say what the papers report.
lung adenocarcinoma (1 paper, 2021). A carcinoma that arises from the lung and is characterized by the presence of malignant glandular epithelial cells. "The heatmap reveals that HNRNPLL|53258|AT, CA5B|98313|ES, MEGF6|315|ES, and CDKN2A|86000|AP may have positive effects on lung adenocarcinoma while BEST3|23330|AT, TTC39C|44852|AP, AP2B1|40327|AD, LETM2|83399|AT, and MKL1|62348|AP can have adverse effects." (PMID 35004299, 2021).
non-small cell lung carcinoma (1 paper, 2024). A group of at least three distinct histological types of lung cancer, including non-small cell squamous cell carcinoma, adenocarcinoma, and large cell carcinoma. "This study investigates platelet‐related subtypes in non‐small cell lung cancer (NSCLC) and seeks to identify genes associated with prognosis, focusing on the clinical significance of the chloride ion channel gene BEST3." (PMID 39708330, 2024).
retinal diseases (1 paper, 2019). "BEST-3 is homologous to the mammalian chloride channel bestrophin, essential for Ca++ signaling in muscles, neurons, and eyes, and defective in retinal diseases." (PMID 30885922, 2019).
tumor (3 papers, 2004 to 2024). "BEST3 had been observed to be present in multiple types of cancerous tissues, and its expression level appears to be linked with the tumor’s capacity for invasion." (PMID 39691708, 2024). "The discovery of three platelet subtypes and the role of BEST3 in promoting tumour growth and migration highlights its potential as a therapeutic target and prognostic marker in NSCLC." (PMID 39708330, 2024). "Through TCGA data analysis, we observed a significant downregulation of BEST3 in adjacent non‐cancerous tissues compared to tumour tissues, indicating a potential role of BEST3 in NSCLC development and progression." (PMID 39708330, 2024). "BEST3 overexpression promotes tumour cell proliferation and migration while inhibiting apoptosis, highlighting its potential as a therapeutic target and prognostic biomarker in NSCLC." (PMID 39708330, 2024). "Furthermore, the correlation between the expression level of BEST3 and the efficacy of tumor therapy has prompted its investigation as a potential therapeutic target or biomarker." (PMID 39691708, 2024). "The validation of BEST3 upregulation in the platelets of cancer patients using PltDB data, along with its substantial overexpression confirmed by FCM, points to its significance within the tumour microenvironment." (PMID 39708330, 2024).
cancer (2 papers, 2023 to 2024). A tumor composed of atypical neoplastic, often pleomorphic cells that invade other tissues. "Further supporting this notion, Cox regression analysis across pan‐cancer datasets revealed that elevated BEST3 expression was linked to poorer prognosis, especially in LUAD, where higher expression levels corresponded to significantly worse survival outcomes." (PMID 39708330, 2024). "Future research focusing on the biological pathways associated with BEST3 could further elucidate its role in cancer biology and enhance its clinical applicability." (PMID 39708330, 2024). "Our findings reveal abnormal BEST3 expression in cancer patients, validated through FCM and TCGA data, suggesting its potential as a clinical indicator for NSCLC progression and prognosis." (PMID 39708330, 2024).
BEST3 also shares sentences with these, for which no sentence is quoted: hyperglycaemia (1 paper); Hypertension (1); periodontitis (1).